RNU6-247P (RNA, U6 small nuclear 247, pseudogene)
Gene: Small nuclear RNA gene on chromosome 12 (95,792,529 to 95,792,635, reverse strand). Ensembl gene ENSG00000199506.
Homologues: Orthologues: chimpanzee U6 (99% identical), macaque U6 (97% identical), pig U6 (78% identical). Paralogues in human: RNU6-393P (89% identical), RNU6-1145P (88% identical), RNU6-16P (88% identical), RNU6-38P (88% identical), RNU6-618P (88% identical), RNU6-20P (87% identical), RNU6-1181P (86% identical), RNU6-25P (86% identical), RNU6-29P (86% identical), RNU6-41P (86% identical), RNU6-44P (86% identical), RNU6-480P (86% identical), and 1288 more.